ACSL1 (acyl-CoA synthetase long chain family member 1)
Description:
Catalyzes the conversion of long-chain fatty acids to their active form acyl-CoAs for both synthesis of cellular lipids, and degradation via beta-oxidation. Preferentially uses palmitoleate, oleate and linoleate. Preferentially activates arachidonate than epoxyeicosatrienoic acids (EETs) or hydroxyeicosatrienoic acids (HETEs) (By similarity).
Synonyms: ACS1; FACL1; FACL2; LACS; LACS1; LACS2
Tractability: Small molecule: a high-quality ligand is known. Antibody: UniProt predicts a signal peptide or a membrane-spanning region. PROTAC: ubiquitination databases record sites on it; its protein half-life has been measured; a small molecule that binds it is known.
Target class: Enzyme; Ligase
Gene: Protein-coding gene on chromosome 4 (184,755,501 to 184,826,853, reverse strand). Ensembl gene ENSG00000151726.
Subcellular location: Mitochondrion outer membrane; Peroxisome membrane; Microsome membrane; Endoplasmic reticulum membrane
Subcellular location (Human Protein Atlas): Vesicles
Pathways (Reactome):
Metabolism: Linoleic acid (LA) metabolism; PPARA activates gene expression; Synthesis of very long-chain fatty acyl-CoAs; alpha-linolenic acid (ALA) metabolism
Gene expression (Transcription): MLL4 and MLL3 complexes regulate expression of PPARG target genes in adipogenesis and hepatic steatosis
Gene Ontology:
Molecular function: long-chain fatty acid-CoA ligase activity; arachidonate-CoA ligase activity; oleoyl-CoA ligase activity; phytanate-CoA ligase activity; pristanate-CoA ligase activity
Biological process: fatty acid transport; lipid biosynthetic process; long-chain fatty acid import into cell; long-chain fatty acid metabolic process; long-chain fatty-acyl-CoA biosynthetic process; positive regulation of cold-induced thermogenesis; positive regulation of long-chain fatty acid import across plasma membrane; very long-chain fatty acid metabolic process; fatty acid metabolic process; response to nutrient; response to oleic acid; response to xenobiotic stimulus; triglyceride biosynthetic process; xenobiotic catabolic process
Cellular component: endoplasmic reticulum; endoplasmic reticulum membrane; membrane; mitochondrion; mitochondrial outer membrane; peroxisomal membrane
Genetic constraint (gnomAD): Loss-of-function variants: 40 observed, 93.74 expected, observed/expected ratio (o/e) 0.43, 90% interval 0.33 to 0.56. The upper end of that interval is the gene's LOEUF score, 0.56, which puts it in group 2 of 6, group 1 being the genes least tolerant of losing a copy. Missense variants: 705 observed, 882.01 expected, observed/expected ratio (o/e) 0.8, 90% interval 0.75 to 0.85. Synonymous variants: 304 observed, 328.29 expected, observed/expected ratio (o/e) 0.93, 90% interval 0.84 to 1.02.
Homologues: Orthologues: chimpanzee ACSL1 (97% identical), macaque ACSL1 (96% identical), dog ACSL1 (92% identical), pig ACSL1 (91% identical), guinea pig ACSL1 (90% identical), rat Acsl1 (86% identical), mouse Acsl1 (85% identical), tropical clawed frog acsl1 (76% identical), zebrafish acsl1a (70% identical), zebrafish acsl1b (65% identical), Caenorhabditis elegans acs-15 (37% identical), Caenorhabditis elegans acs-18 (36% identical), and 22 more. Paralogues in human: ACSL6 (67% identical), ACSL5 (59% identical), ACSL3 (32% identical), ACSL4 (29% identical), ACSBG1 (24% identical), ACSBG2 (23% identical), SLC27A2 (18% identical), SLC27A4 (18% identical), SLC27A5 (18% identical), SLC27A6 (18% identical), SLC27A1 (17% identical), SLC27A3 (16% identical).
Diseases named in the same sentence as ACSL1 in open-access papers:
ACSL1 is named in the same sentence as 123 diseases in open-access papers, as found by Europe PMC text mining. Sharing a sentence is not in itself a finding about the gene and the disease. The quoted sentences say what the papers report.
breast carcinoma (26 papers, 2016 to 2026). "ACSL1 regulates the TNFα- and LPS-induced GM-CSF production in breast cancer MDA-MB-231 cells, suggesting the role of ACSL1 in the regulation of growth-modulating cytokines or embryokines." (PMID 34299302, 2021). "As previously stated, ACSL1 is upregulated in breast cancer, and its expression correlates with poor survival." (PMID 31344914, 2019). "RNAi experiments show that ACSL1 targeting reduces proliferation, colony formation and cell viability in breast cancer cell lines, thus rendering ACSL1 an attractive therapeutic target for breast, as well as colorectal cancer." (PMID 31344914, 2019). "In accordance with PrognoScan analysis, downregulation of ACSL1 in colon and breast cancer cell line inhibited proliferation, migration, and anchorage-independent growth." (PMID 27171439, 2016). "The probe 201963 for ACSL1 was used in analyzing the prognostic value in breast cancer and lung cancer patients." (PMID 27171439, 2016). "Altogether, the prediction of oncogenic role of ACSL1 from PrognoScan and Kaplan-Meier plotter in breast cancer is supported by the in vitro experimental assay." (PMID 27171439, 2016). "disclosed that breast cancer patients with high levels of ACSL1 tended to have a poor prognosis." (PMID 37608295, 2023). "Notably, all the FA metabolic genes ELOVL6, ACSL1, ACSL3, ACSL4, ACDSB and ACAT1 showed significant positive correlation with NAT10 suggesting that overexpression of NAT10 in breast cancer patients is associated with FA metabolism." (PMID 36149760, 2022). "It was reported that decreased ACSL1 could suppress the protumorigenic inflammatory responses induced by granulocyte–macrophage colony-stimulating factor (GM-CSF) in breast cancer." (PMID 34268107, 2021). "ACSL1 may play a potential oncogenic role in colorectal and breast cancer and play a potential tumor suppressor in lung cancer." (PMID 34823530, 2021). "ACSL1 may play a potential oncogenic role in colorectal and breast cancer and play a potential tumor suppressor role in lung cancer." (PMID 27171439, 2016). "ACSL1 was upregulated in colorectal cancer, but decreased in lung and breast cancer." (PMID 27171439, 2016). "While ACSL1 has been shown to support the proliferation of both colorectal cancer (CRC) and breast cancer (BC) cell lines, other evidence implicates ACSL1 as a tumor suppressor in non‐squamous cell lung carcinoma (NSCLC) cells." (PMID 39853696, 2025). "A substantial body of evidence has demonstrated that the PPARα agonist clofibrate enhances the biological activities of ACSL1 and CPT1 enzymes, thereby facilitating FAO in breast cancer cells." (PMID 40002245, 2025). "Copy number deletion and downregulated expression of ACSL1 and upregulation of SRD5A3 both were observed in breast cancers." (PMID 35739271, 2022). "This analysis concluded that ACSL1 was upregulated in CRC but diminished in lung and breast cancer, as well as in the brain, cervical, esophageal, head and neck, leukemia, liver, and sarcoma cancers." (PMID 33050166, 2020). "In aggressive prostate and breast cancer cells, FABP5 knockdown repressed the expression of genes involved in lipolysis, including HSL and MAGL, as well as that of genes involved in de novo FA synthesis, such as ELOVL6 and ACSL1." (PMID 33128030, 2020). "Besides, systematic analysis of ACSLs expression and clinical outcomes in several human cancers points towards ACSL1 upregulation in CRC and breast cancer and downregulation in lung cancer." (PMID 28894242, 2017). "Interestingly, the data obtained from Oncomine indicated that ACSL1 may function as a tumor suppressor gene in breast cancer; however, the data obtained from PrognoScan and Kaplan-Meier plotter indicated that ACSL1 may play a potential oncogene in breast cancer." (PMID 27171439, 2016). "ACSL1 may be different from other ACSL family members, and play a pro-oncogenic role in breast cancer as demonstrated by PrognoScan and in vitro analysis." (PMID 27171439, 2016).
breast carcinoma (continued). "For instance, ACSL1 is up-regulated in colorectal cancer and estrogen receptor (ER)-negative, ER-positive and HER2-positive breast cancer subtypes, and high ACSL1 expression in these patients’ tumor samples is linked to unfavorable prognosis." (PMID 37608295, 2023). "ACSL1 results to be transcriptionally upregulated in both estrogen receptor (ER)-negative, ER-positive and HER2-positive breast cancer subtypes, and its mRNA levels correlate with poor patient survival, but the specific mechanisms and functional significance of their upregulation are unclear." (PMID 31344914, 2019).
hepatocellular carcinoma (25 papers, 2014 to 2025). A malignant tumor that arises from hepatocytes. "Among the down-regulated genes, ACSL1 encodes the long-chain fatty acid CoA synthetase and is associated with an increased risk of hepatocellular carcinoma." (PMID 38957470, 2024). "Targeting the 3’UTR causes down-regulation of ACSL1 expression and cholesterol accumulation in hepatoma cells, which results in abnormal lipid metabolism." (PMID 37746253, 2023). "Recently, miR-205 has been associated with lipid metabolism de-regulation in hepatocellular carcinoma, acting on acyl-CoA synthetase long-chain family member 1 (ACSL1), a lipid metabolism enzyme in liver." (PMID 27551267, 2016). "ACSL1, encoding an isozyme of the long-chain fatty-acid-coenzyme in a ligase family, is downregulate by MiR-27a-3p and MiR-205 to increase the risk of liver cancer and hepatocellular carcinoma respectively." (PMID 36968582, 2023). "Supporting these findings, in vitro experiments demonstrated that HULC activates ACSL1 expression in HepG2 hepatoma cells via the miRNA-9/PPARA signaling pathway, thereby inducing lipid metabolic reprogramming that facilitates HCC progression." (PMID 40909946, 2025). "ACSL1 exhibits elevated expression levels in hepatocellular carcinoma, BC, ovarian cancer, and colorectal cancer, while displays low expression in esophageal adenocarcinoma and renal cell carcinoma." (PMID 40337509, 2025). "It has also been reported that the over-expression of ACSL1 leads to the production and accumulation of large amounts of TG in hepatoma cells." (PMID 35804549, 2022). "In hepatocellular carcinoma, ACSL1 promotes the fat metabolism of the tumor and the progression of the disease by catalyzing the ATP-dependent acylation of fatty acids into long-chain acyl CoAs (LCA-CoAs)." (PMID 34268107, 2021). "Studies in hepatocellular carcinoma have shown that long-chain noncoding RNA HULC can activate ACSL1 by upregulating the transcription factor PPARA to affect the proliferation of liver cancer cells." (PMID 33688464, 2021). "This study indicated that human hepatocellular carcinoma cells (HepG2) overexpressing ACSL1 had 40% higher triglyceride content than the control group after 24 hours of exposure to 1.0mM oleic acid ester." (PMID 32218693, 2020). "Another study uncovered that miR-205 deregulates lipid metabolism through targeting acyl-CoA synthetase long-chain family member 1 in hepatoma cells." (PMID 31315616, 2019). "In this case, HULC stimulates the accumulation of intracellular triglycerides and cholesterol through the miR-9/PPARα/ACSL1 signaling pathway in hepatoma cells." (PMID 30134946, 2018). "Considering that NF-κB activation was responsible for the explosive expression of various inflammatory genes, and NF-κB inhibition suppressed ACSL1 expression in hepatocellular carcinoma cells, we checked whether NF-κB inhibition attenuated ACSL1 expression." (PMID 34960652, 2021). "HULC upregulates the transcriptional factor peroxisome proliferator-activated receptor alpha (PPARA) which increases acyl-CoA synthetase long-chain family member 1 (ACSL1), leading to triglycerides and cholesterol production and proliferation of hepatoma cells." (PMID 28840253, 2018). "In hepatocellular carcinoma (HCC), lncRNA HULC forms a positive feedback loop to promote adipogenesis and enhance tumor proliferation through the HULC/miR-9/PPARA/ACSL1/cholesterol/RXRA/HULC pathway." (PMID 36452489, 2022). "In hepatoma cells, HULC suppresses miR-9 targeting PPARα silencing by eliciting the methylation of CpG islands in the miR-9 promoter, and PPARα activates ACSL1 transcription." (PMID 30134946, 2018). "In the liver, overexpression of ACSL1 results in increased proportion of oleic acid in diacylglycerol (DAG) and phospholipids (PLs), and promotes synthesis of triglyceride (TG) from free fatty acids and its accumulation in hepatoma cells." (PMID 32442168, 2020).
hepatocellular carcinoma (continued). "LncHULC is highly expressed in hepatocellular carcinoma (HCC) patient tissues and positively correlated with the lipogenic gene ACSL1, which in turn controls intracellular triglycerides and cholesterol levels by increasing the miR-9-PPARA-ACSL1 axis." (PMID 31416244, 2019). "Acyl-CoA synthase long-chain (ACSL) family members catalyze the initial step in cellular long-chain FA metabolism in mammals; ACSL1, one of the major isoforms of the ACSL family, can increase the uptake of FAs in hepatoma cells and can be regulated by the transcriptional factor PPARα." (PMID 30134946, 2018). "Hepatocellular carcinoma upregulated long non-coding RNA (HULC) is highly upregulated in hepatocellular carcinoma and sequesters several miRNAs, including miR-9, leading to de-repression of its target, PPARA, which induces a positive feedback loop involving ACSL1." (PMID 27487126, 2017). "For example, the Highly Up-Regulated In Liver Cancer long non-coding RNA (LncRNA-HULC) is able to activate acyl-CoA synthetase subunit ACSL1, involving also in this process miR-9 and PPARA, contributing to the malignant development of hepatocellular carcinoma (HCC)." (PMID 33050166, 2020). "First, among ACSL family members, AA treatment markedly and selectively reduced ACSL4 protein levels without affecting cellular levels of ACSL1 and ACSL5 in model hepatoma cell lines, including HepG2 and Huh7 cells as well as in primary mouse hepatocytes." (PMID 24879802, 2014).
Obesity (22 papers, 2015 to 2026). Accumulation of substantial excess body fat. "Dysfunction of ACSL1 has been linked to conditions such as cardiac dysfunction, obesity, sepsis, and various cancers." (PMID 39908200, 2025). "In obesity-related kidney disease models, the downregulation of long-chain acyl-CoA synthetase-1 (ACSL1), a vital enzyme in fatty acid oxidation, is closely linked to heightened lipid accumulation in the kidneys." (PMID 40584092, 2025). "As induction of skeletal muscle insulin resistance is correlated with excessive fat accumulation and obesity, it is important to assess the ACSL1-mediated lipid metabolism under the HFD-induced IR state." (PMID 39178212, 2024). "For example, in an animal model of high-fat-induced obesity, the expression of ACSL1 and HMGCS1 was inhibited in both hamster and zebrafish livers, and steatosis also occurred in the livers of these animals." (PMID 37239994, 2023). "The content of total ACS mRNA, as well as ACSL1 mRNA, were lower in muscle of males/females with obesity and T2D." (PMID 37726199, 2023). "Correlations between genes and weight loss were observed in two genes with known roles in obesity: FOXP2 (cg18546840 R = 0.85) and ACSL1 (cg00287477 R = 0.91)." (PMID 25651499, 2015). "Although ACSL1 clearly plays an important role in lipid metabolism, insulin resistance, and obesity, no studies so far have investigated the association between ACSL1 and DKD." (PMID 38016515, 2023). "ACSL-1 may be regulated by dietary fat consumption raising the importance of adequate nutritional strategy in obesity treatment." (PMID 33716957, 2021). "Future research could consider a pharmacological obesity co-treatment by triacsin C with evaluation of its cardioprotective effects because this fungal metabolite has been recognized as ACSL-1 inhibitor." (PMID 33716957, 2021). "Acsl-1 gene modulation may be a potential therapeutic strategy in obesity-related cardiomyopathy and Acsl-1 haploinsufficiency resulted in normalization of cardiac lipid storage in db/db mice." (PMID 33716957, 2021). "ACSL1 is upregulated by LPS and TNFα, both of which are elevated in obesity." (PMID 34299302, 2021). "In obesity-related nephropathy models, reduced NRF2 along with suppressed expression of the key FAO enzyme long-chain acyl-CoA synthetase-1 (ACSL1) are associated with elevated renal lipid deposition, further supporting the importance of mitochondria in lipid metabolism and energy homeostasis." (PMID 33013450, 2020). "Accordingly, S1PR3, IQCG, and TF are common in HCL, aging, and CVD; ACSL1, THBD, and HNF4A are repeated in HTN, obesity, and CVD." (PMID 36035865, 2022). "Downregulation of ACSL1 enhances insulin sensitivity and glucose uptake by reducing long-chain acyl-CoA (LCA-CoA), ceramide (Cer), and diacylglycerol (DAG) levels, thereby alleviating obesity." (PMID 41288931, 2025). "Inhibiting ACSL1 in monocytes suppressed the TNF-α-induced expression of CD11c, which is a highly expressed inflammatory marker on monocytes and macrophages during conditions of obesity." (PMID 34299302, 2021). "The results of this study pinpoint ACSL1 as the most prominent transcribed ACS enzyme in human skeletal muscle, independent of the presence of obesity or insulin resistance." (PMID 37726199, 2023).